HULC (hepatocellular carcinoma up-regulated long non-coding RNA)
Diseases named in the same sentence as HULC in open-access papers (continued):
Sharing a sentence is not in itself a finding about the gene and the disease.
liver cancer (continued). "Thus, we conclude that lncRNA HULC might be related to the angiogenesis in liver cancer by the up-regulation of SPHK1." (PMID 26540633, 2016). "However, this action of MALAT1 combined with HULC was abrogated in liver cancer stem cell lines transfected with pCMV6-A-GFP-HULC plus pCMV6-A-GFP-MALAT1 plus pFGP-V-RS—TRF2 or pGFP-V-RS-GFP-HULC plus pGFP-V-RS–MALAT1 plus pcDNA-CREPT (39.5%, 41.5% vs 43.7%, respectively, P > 0.05)." (PMID 27782152, 2016). "HULC (highly upregulated in liver cancer) is an lncRNA specifically overexpressed in HCC; HULC upregulates PPARα to activate acyl-CoA synthetase subunit ACSL1, thereby aberrantly modulating lipid metabolism in hepatoma cells and in the development of HCC." (PMID 39199690, 2024). "HULC (Highly Upregulated in Liver Cancer): Overexpressed in exosomes from CRC and liver cancer, HULC accelerates the progression of CRC by targeting miR-613 to stimulate cell proliferation and inhibit apoptosis." (PMID 37760852, 2023). "For example, lncRNA HULC interacts with miR-186 to promote HMGA expression, leading to liver cancer progression." (PMID 33589577, 2021). "HULC enhances CyclinD1 and thereby increases pRB and inhibited P21 WAF1/CIP 1 via autophagy-miR675-PKM2 pathway in human liver cancer stem cells." (PMID 31900225, 2020). "HULC enhances CyclinD1 and thereby increases pRB and inhibited P21 WAF1/CIP 1 via autophagy-Pyruvate Kinase M2 (PKM2) pathway in human liver cancer stem cells." (PMID 31900225, 2020). "Collectively, these observations suggest that HULC enhances CyclinD1 to increase pRB and inhibit P21 WAF1/CIP 1 via autophagy-PKM2 pathway in human liver cancer stem cells." (PMID 31900225, 2020). "HULC enhances CyclinD1 and thereby increases pRB and inhibited P21 WAF1/CIP 1 via autophagy-PKM2 pathway in human liver cancer stem cells." (PMID 31900225, 2020). "It has been reported that lncRNAs including HULC, HOTAIR and LncTCF7 are highly expressed in liver cancer samples 27, 31-33." (PMID 31695772, 2019). "Taken Together, these observations suggest HULC was over-expressed and miR15a or PTEN was down-expressed inhuman liver cancer tissue." (PMID 29895332, 2018). "Together, these results suggest that HULC and MALAT1 accelerates the liver cancer stem cells proliferation." (PMID 27782152, 2016). "Intriguingly, MALAT1 combined with HULC resulted in the greater effeciency in stable liver cancer stem cell lines transfected pCMV6-A-GFP, pCMV6-A-GFP-HULC, pCMV6-A-GFP-MALAT1, pCMV6-A-GFP-HULC plus pCMV6-A-GFP-MALAT1 (upper)." (PMID 27782152, 2016). "HULC overexpression, MALAT1 overexpression, HULC overexpression plus MALAT1 overexpression promoted liver cancer stem cell cell proliferation compared to control (t-test, P < 0.01)." (PMID 27782152, 2016). "Intriguingly, MALAT1 combined with HULC resulted in the greater effeciency in stable liver cancer stem cell lines transfected pCMV6-A-GFP, pCMV6-A-GFP-HULC, pCMV6-A-GFP-MALAT1, pCMV6-A-GFP-HULC plus pCMV6-A-GFP-MALAT1." (PMID 27782152, 2016). "Collectively, these findings demonstrate that HULC and/or MALAT1 enhances liver cancer stem cells’ progression in vivo." (PMID 27782152, 2016). "Intriguingly, MALAT1 combined with HULC resulted in the greater effeciency in stable liver cancer stem cell lines transfected with pCMV6-A-GFP, pCMV6-A-GFP-HULC, pCMV6-A-GFP-MALAT1, pCMV6-A-GFP-HULC plus pCMV6-A-GFP-MALAT1." (PMID 27782152, 2016). "Together, these observations suggest MALAT1, HULC and TRF2 were overexpressed in liver cancer tissue, and there was positively correlation among the expression of MALAT1, HULC and TRF2 in human primary liver cancer." (PMID 27782152, 2016).
liver cancer (continued). "Moreover, HULC promotes autophagy through the miR-675/PKM2 axis, leading to upregulation of Cyclin D1 and accelerated proliferation of liver cancer stem cells." (PMID 40909946, 2025). "Similarly, via the miR-9/PPARA signaling pathway, HULC activates ACSL1 and induces abnormal lipid metabolism in liver cancer cells, contributing to disease progression." (PMID 40909946, 2025). "Therefore, HULC increases the cellular autophagy by increasing LC3II dependent on Sirt1.Noteworthy, excessive HULC reduces the expression of PTEN, β-catenin and enhances the expression of SAPK/JUNK, PKM2, CDK2, NOTCH1, C-Jun in liver cancer cells." (PMID 29895332, 2018). "Strangely, HULC, which was named as highly up-regulated in liver cancer, was not significantly differentially expressed." (PMID 28496001, 2017). "Furthermore, HULC, MALAT1 overexpression promotes the growth of liver cancer stem cells in vitro and in vivo." (PMID 27782152, 2016). "Previous studies reported HULC was a negative prognostic factor for liver cancer, and our clinical data showed similar results that HULC expression in HCC tissues was significantly increased as compared with that observed in normal liver tissues." (PMID 27285757, 2016). "HULC was significantly overexpressed in pCMV6-A-GFP-HULC, pCMV6-A-GFP-HULC plus pCMV6-A-GFP-MALAT1 transfected liver cancer stem cells compared the control, and MALAT1 were significantly overexpressed in pCMV6-A-GFP-MALAT1, pCMV6-A-GFP-HULC plus pCMV6-A-GFP-MALAT1 transfected liver cancer stem cell." (PMID 27782152, 2016). "To explore whether the oncogenic function of the MALAT1 and/or HULC is dependent on TRF2, we preformed the rescued experiment in liver cancer stem cell line." (PMID 27782152, 2016). "HULC (highly upregulated in liver cancer), 1.6 k nucleotide long, containing two exons but not translated, has been identified highly upregulated in HCC and colorectal cancer that metastasized to livers." (PMID 26136615, 2015). "Moreover, we have clearly demonstrated that MEG3 inhibits METTL3 through blocking HULC in human liver cancer (data not shown)." (PMID 33425489, 2021). "Moreover, we have demonstrated that linear MEG3 inhibits METTL3 through blocking HULC in human liver cancer (data not shown)." (PMID 33425489, 2021). "HULC, which is significantly upregulated in hepatocellular carcinoma, can reduce the expression and activity of miR-372 in liver cancer, which derepresses the translation of its target gene PRKACB and induces phosphorylation of the cAMP response element binding protein in liver cancer." (PMID 32256525, 2020). "For example, HULC (Highly Upregulated in Liver Cancer) is expressed at high levels in HCC and colorectal carcinomas that have metastasized to the liver, but not in primary colon tumors or non-liver metastases, with increased plasma HULC levels observed in 63 % of HCC patients." (PMID 27189224, 2016).
gastric cancer (26 papers, 2014 to 2025). A primary or metastatic malignant neoplasm involving the stomach. "Up‐regulation of HULC was associated with poor pathological and clinical outcome in osteosarcoma, pancreatic cancer and gastric cancer." (PMID 27781386, 2017). "In vivo, silencing HULC significantly inhibited tumor growth in a mouse xenograft model of gastric cancer." (PMID 40909946, 2025). "In gastric cancer, HULC promotes cell proliferation, migration, invasion and resistance to apoptosis through the miR-9-5p/MYH9 axis." (PMID 40909946, 2025). "In vitro, overexpression of HULC promotes the proliferation and invasion of human gastric cancer cells, while inhibiting cell apoptosis." (PMID 40909946, 2025). "Inhibition of HULC enhances cisplatin-induced apoptosis in gastric cancer cells, and the HULC/FoxM1 signaling pathway has been shown to promote cisplatin resistance by inducing autophagy." (PMID 40909946, 2025). "Taken together, these findings highlight HULC as an important regulator of tumor growth, metastasis, and drug resistance in gastric cancer." (PMID 40909946, 2025). "HULC, H19, HOTAIR, and GACAT2 (for “gastric cancer-associated transcript 2”) were found to be significantly increased in the plasma of gastric cancer (GC) patients compared to healthy individuals." (PMID 37190024, 2023). "In gastric cancer, high expression of HULC promotes cell proliferation, inhibits apoptosis of cancer cells, and enhances tumor metastasis." (PMID 36213832, 2022). "LncRNA HULC knockdown repressed gastric cancer progression, at least partly by regulating the miR-9-5p/MYH9 axis." (PMID 35646686, 2022). "HULC expression is a predictor of poor prognosis across multiple cancers, and HULC silencing enhanced the effectiveness of chemotherapy in stomach cancer cell lines." (PMID 33769711, 2021). "As expected, silencing HULC has been shown to inhibit autophagy and enhance chemotherapy sensitivity of gastric cancer cells in vitro and in vivo." (PMID 32460771, 2020). "Previous studies have shown that HULC silencing inhibits the growth of gastric cancer cells and weakens their drug resistance." (PMID 31645479, 2019). "Since its discovery, the aberrant up‐regulation of HULC has been demonstrated in other cancer types, including gastric cancer, pancreatic cancer, osteosarcoma and hepatic metastasis of colorectal cancer." (PMID 27781386, 2017). "Moreover, high levels of HULC expression have been described in liver metastases in colorectal carcinoma patients, and its expression has been associated with lymph node metastasis and vascular infiltration in pancreatic cancer and advanced metastatic disease in gastric cancer." (PMID 27253450, 2016). "For example, a study demonstrated that HULC was significantly overexpressed in gastric cancer cell lines and gastric cancer tissues compared with normal tissues, and its overexpression was correlated with distant metastasis and lymph node metastasis." (PMID 25496320, 2014). "For instance, HULC was found to interact with FoxM1 and modulate the protein level of FoxM1 by inhibiting its ubiquitination process and stabilizing its expression, thereby mitigating cisplatin resistance in gastric cancer." (PMID 38927012, 2024). "In DDP-resistant gastric cancer cells, overexpressed METase could downregulate the expression of lncRNA HULC, thus decreasing the protein level of FoxM1 and suppressing autophagy and cisplatin resistance." (PMID 38927012, 2024). "In addition, lncRNAs GHET 1, AK022798, antisense non-coding RNA in the INK4 locus (ANRIL), UCA 1 and HULC also conferred DDP resistance of gastric cancer cells via modulating expression of multiple drug resistance-related genes." (PMID 32192494, 2020). "In addition to its influence in HCC, HULC also plays an important role in the growth and tumorigenesis of human gastric cancer (GC)." (PMID 27285757, 2016).
gastric cancer (continued). "Interestingly, HULC could serve as a serum biomarker for the diagnosis and prognosis of gastric cancer." (PMID 34439315, 2021). "For instance, lncRNA ANRIL was reported to encourage proliferation of gastric carcinoma cells by silencing miR-99a and miR-449a, while miR-372 down-regulated expression of lncRNA HULC in hepatoma carcinoma cells by disaggregating transcriptional factors from the promoter of HULC." (PMID 32143722, 2020). "Further studies have demonstrated that HULC enhances proliferation, EMT, migration, and invasion of gastric cancer cells through the miR-9-5p/MYH9 axis." (PMID 40909946, 2025). "Moreover, HULC, H19, HOTAIR and GACAT2 (for “gastric cancer-associated transcript 2”) were found to be significantly increased in the plasma of gastric cancer (GC) patients compared to healthy individuals." (PMID 35729321, 2022). "Multiple onco-lncRNAs, such as HOTAIR, CASC9, MRUL, UCA1, D63785, NEAT1 and HULC, are involved in ADR resistance in gastric cancer." (PMID 32192494, 2020). "Positive regulation of EMT, manifested as down‐regulation of epithelial markers (e.g. E‐cadherin) and up‐regulation of mesenchymal markers (e.g. vimentin), by HULC has been demonstrated in HCC 29 and gastric cancer." (PMID 27781386, 2017). "Knockdown of HULC inhibited proliferation, invasion and EMT, and promoted cell apoptosis in SGC-7901 gastric cancer cells." (PMID 25496320, 2014). "Additionally, HULC and NEAT1 contribute to the development of gastric cancer cells' increased ADR resistance." (PMID 38294554, 2024). "The findings from this study indicate that HULC, RP11‐314B1.2, LINC00106, and RP11‐999E24.3 could be considered as potential therapeutic targets or prognostic biomarkers in gastric cancer, and provide a new perspective for cancer pathogenesis research." (PMID 31923354, 2020).
colorectal cancer (17 papers, 2013 to 2025). A primary or metastatic malignant neoplasm that affects the colon or rectum. "Kaplan-Meier survival analysis showed that the upregulation of HULC was significantly associated with poor prognosis in patients with colorectal cancer." (PMID 40909946, 2025). "Accumulating evidence shows that HULC is aberrantly expressed in various gastrointestinal malignancies, including liver, gastric, and colorectal cancers." (PMID 40909946, 2025). "HULC expression was significantly upregulated in human primary colorectal cancer and colorectal cancer cell lines." (PMID 40909946, 2025). "It was reported that HULC expression is increased in colorectal cancers and is involved with accelerated growth of colon cancer cells through targeting miR-61339." (PMID 38360831, 2024). "In colorectal cancer, HULC interacts with EZH2, leading to the inhibition of the transcription of the target NKD2, which, in turn, activates the WNT signaling pathway to promote carcinogenesis." (PMID 39408810, 2024). "A typical example of “miRNA sponges” is HULC, which is over-expressed in colorectal carcinomas that could metastasize to the liver." (PMID 26637808, 2016). "However, whether hepatic microenvironment drives the overexpression of HULC or HULC by itself could promote liver metastasis of colorectal cancer remains to be ascertained." (PMID 27781386, 2017). "Interestingly, HULC not only affects the occurrence of HCC, but also has a role in colorectal cancer." (PMID 39408810, 2024). "Surprisingly, they found that colorectal cancer with hepatic metastasis, but not lymph nodes metastasis, exhibited a significant up‐regulation of HULC." (PMID 27781386, 2017). "This is the case of HULC, a liver-specific lncRNA highly expressed in primary liver tumours and hepatic metastases of colorectal carcinoma, but not found in primary colon cancers or in non-liver metastases." (PMID 23887658, 2013). "In addition, HULC expression is not only confined to HCC, but is also expressed in colorectal carcinomas that metastasize to the liver." (PMID 24063685, 2013).
osteosarcoma (14 papers, 2016 to 2025). A usually aggressive malignant bone-forming mesenchymal neoplasm, predominantly affecting adolescents and young adults. "Therefore, we evaluated the expression of HULC in primary osteosarcoma samples at diagnosis and its association with the clinicopathological characteristics of OS Brazilian patients." (PMID 27253450, 2016). "HULC knockdown notably inhibited the migration of osteosarcoma cell lines, including SAOS-2 and MG63." (PMID 36213832, 2022). "HULC knockdown markedly inhibited the invasion of osteosarcoma cell lines, including SAOS-2 and MG63." (PMID 36213832, 2022). "In CCK-8 assay, we found that HULC knockdown significantly reduced cell proliferation in osteosarcoma cell lines." (PMID 36213832, 2022). "In conclusion, this study supported that the expression of lncRNA HULC was increased in osteosarcoma, which enhanced the progression of osteosarcoma in vivo and in vitro." (PMID 36213832, 2022). "Overexpression experiment was performed to detect the effect of HULC in osteosarcoma cell proliferation." (PMID 36213832, 2022). "This study reflected that downregulation of HULC impeded the proliferation, migration, and invasion of osteosarcoma cells." (PMID 36213832, 2022). "The present study also found that the expression of lncRNA HULC was obviously increased in human osteosarcoma tissues and cells." (PMID 36213832, 2022). "HULC is also aberrantly up-regulated in a wide spectrum of malignancies, including liver cancer, prostate cancer, ovarian cancer, bladder cancer, osteosarcoma, gastric cancer, and myeloid leukemia." (PMID 32010942, 2020). "For example, lncRNA HULC expression was up-regulated in osteosarcoma tissues and cell lines, and the higher expression of HULC was associated with poor prognosis of osteosarcoma patients." (PMID 29568404, 2018). "Till now, the prognostic roles of multi-types of lncRNAs have been investigated in osteosarcoma as well, consisting of HULC, HOTTIP, MEG3, TUSC7, TUG1, 91H, and OMRUL, etc." (PMID 28415638, 2017). "Then, the effect of downregulation HULC on osteosarcoma cells was investigated." (PMID 36213832, 2022). "HULC overexpression markedly increased osteosarcoma cell proliferation and tumor size in vivo." (PMID 36213832, 2022). "HULC was overexpressed in human osteosarcoma cell which has been shown in the previous studies." (PMID 36213832, 2022). "In addition, HULC overexpression markedly increased osteosarcoma cell proliferation and tumor size in vivo." (PMID 36213832, 2022). "The present study was investigating the role of HULC in malignant behaviors of osteosarcoma." (PMID 36213832, 2022). "Furthermore, HULC increased the activity of AKT-PI3K-mTOR pathway by blocking PTEN in osteosarcoma cells." (PMID 36213832, 2022). "Moreover, cell proliferation, migration, and invasion were inhibited by HULC knockdown in osteosarcoma cells." (PMID 36213832, 2022). "Knockdown of HULC could inhibit proliferation, migration, invasion, and promote apoptosis by sponging miR-122 in osteosarcoma." (PMID 32010942, 2020). "Hence, we designed this research to explore the function of HULC in osteosarcoma." (PMID 36213832, 2022). "Among those cancers, lncRNAs are more widely researched in osteosarcoma, including lncRNA-21A, UCA1, MEG3, HULC, and MIR31HG." (PMID 36057712, 2022). "For example, nine lncRNAs (91H, FGFR3-AS1, BCAR4, TUG1, UCA1, HIF2PUT, HOTTIP, HULC, and MALAT-1) are up-regulated in osteosarcoma, which is considered oncogenic for osteosarcoma." (PMID 31850493, 2020). "With regard to osteosarcoma, lncRNAs such as HOTAIR, HULC, H19 and MALAT-1, have been identified to be aberrantly expressed in cancer and function with underlying mechanisms." (PMID 31443665, 2019). "The altered lncRNA expression profile possessed a total of 9 individuals, yet 7 of them (TUG1, 91H, HULC, BANCR, FGFR3-AS1, HOTTIP, and OMRUL) were overexpressed in osteosarcoma tissues/plasma, and 2 (MEG3 and TUSC7) were down-regulated." (PMID 28415638, 2017).